HAP1 (huntingtin associated protein 1)
Diseases named in the same sentence as HAP1 in open-access papers (continued):
Sharing a sentence is not in itself a finding about the gene and the disease.
cancer (25 papers, 2004 to 2025). A tumor composed of atypical neoplastic, often pleomorphic cells that invade other tissues. "SETD3 is responsible for the methylation of H73 in human and Drosophila actin, and a loss of SETD3 activity in human HAP1 cells induces phenotypic changes resembling those present in cancer cells, suggesting that the hypomethylation of actin might be involved in tumorigenesis." (PMID 30526847, 2018). "The effect of USP21 deletion in cancer cells was studied in CRISPR/Cas9-edited USP21-targeting HAP-1 cells (HAP-1 USP21 KO) in comparison to HAP-1 parental control (HAP-1 WT)." (PMID 39305962, 2024). "The results demonstrated a reduced colony-forming capacity of the Baz2B-KO cells compared to the control cell line, suggesting that Baz2B plays a role in cancer cell proliferation in the Hap1 cell line." (PMID 38000389, 2024). "Recently, the relationship between HAP1 and certain types of cancer has been increasingly recognized and highlighted, warranting further research and discussion." (PMID 38975245, 2024). "Altogether, these results indicate that Baz2B-KO cells exhibit alterations in the transcriptional landscape during cancer proliferation, while the global chromatin organisation remains similar to that of the parental Hap1 control cell line." (PMID 38000389, 2024). "Despite the fact that the cell context of the study is the Hap1 cell line, a cancer cell line, these results appear to indicate the NHE6-mediated transcriptional changes are prominently recognized as neuronal." (PMID 37747131, 2023). "Being a cancer cell line with a near-haploid genome, HAP1 is prone to genetic instability, which is further compounded by its tendency to diploidise in culture spontaneously." (PMID 36289492, 2022). "In this proof-of-concept study, we used a GPx1 knockout cell line, obtained by a CRISPR-Cas9 deletion of the only GPX1 gene in HAP-1 haploid human cancer cells, to analyze for differences in potency of widely used anticancer drugs to the parental line." (PMID 33353055, 2020). "Loss of either complex inhibited growth of Hap1 cells at neutral pH and caused sensitivity to acid stress, indicating that AP-3 and PAN complexes are promising new targets in the treatment of cancer." (PMID 27519690, 2016). "DE genes identified in HAP1 is reflected in cancer patients." (PMID 37984988, 2024). "Thus, loss of AP-3 and PAN complex function negatively impacted the rate of Hap1 cell growth in culture, suggesting that these complexes were promising cancer targets." (PMID 27519690, 2016). "Thus, over the media pH range studied, Hap1 cell growth seemed to be resistant to acid stress, confirming that it was a good model cancer cell line to study mechanisms of acid stress resistance." (PMID 27519690, 2016). "We selected bacteriophage HAP1, which was able to bind cancer cells more strongly." (PMID 19154575, 2009). "In addition to its role as a cancer biomarker, HAP1 is most likely a tumor suppressor." (PMID 38975245, 2024). "To identify Food and Drug Administration (FDA)-approved drugs that selectively target cancer cells with inactivated RNF43 and PWWP2B genes, we performed a high-throughput screening of 1,449 drugs in HAP1, HAP1 RNF43 KO, and HAP1 PWWP2B KO cells." (PMID 34149925, 2021). "Importantly, based on our preclinical finding, docetaxel trihydrate, pelitinib, and uprosertib have significant anti-cancer effects in cancers with low RNF43 and PWWP2B expression (HAP1 RNF43 KO, HAP1 PWWP2B KO cells, MKN45 cells, and KMN45 xenografts)." (PMID 34149925, 2021). "A subset of common proteins significantly elevated in grade 1, 2 and 3 of cancer patients were identified by nano-electrospray quadrupole quadrupole time-of-flight mass spectrometry (n-ESIQ(q)TOFMS) and MALDI-TOFMS as a series of haptoglobin-1 precursor (HAP1)." (PMID 15199385, 2004).
cancer (continued). "Thus, MRE11 recruitment in HAP-1 cells without external replication stress feasibly could be a reflection of increased intrinsic replication stress in cancer cells compared with primary cells, or alternatively differences between species." (PMID 29475976, 2018). "Notably, in HAP1 cells knocked out for USP11, reintroduction of WT, but not catalytically inactive CS, USP11 resulted in a decreased cancer cell growth, invasion, and glucose and glutamine metabolism." (PMID 30733438, 2019).
infection (19 papers, 2017 to 2025). The state of being infected such as from the introduction of a foreign agent such as serum, vaccine, antigenic substance or organism. "One of these mutants, VSV-∆M51-GFP31, caused a readily measurable response upon infection of HAP1 wild type cells, as shown by phosphorylation of IRF3 and STAT1 transcription factors." (PMID 31320712, 2019). "The BS infection score distribution in each haplotype of OsFBN1 and OsFBN5 median values of haplotypes from hap 3 onwards were significantly lower than those of hap1 and 2, and the number of varieties is only a minority." (PMID 39683095, 2024). "In total, 2.5 × 108 WT HAP1, DCTD KO and TOPORS KO HAP1 cells were infected with the pre-packaged genome-wide All-in-One Brunello lentiviral library (Addgene 73179) at a multiplicity of infection (MOI) of 0.2." (PMID 38760575, 2024). "To more efficiently assess the role of Arf6, here, we used WT, ΔArf6, and ΔNap1 Hap1 cells, and performed a gentamycin protection assay measuring invasion at different times post infection." (PMID 32252226, 2020). "To further characterize the role of IRE1 during MARV infection, we analysed the progression of infection in HAP1 parental (wt) and IRE1 KO cells over a period of 6 days." (PMID 31495285, 2019). "As the membrane-scission protein dynamin interacts with SNX9, we examined the structure of early C. trachomatis-containing vacuoles at 3 hours post infection of HAP1 wild type and SNX9-/- by cryo-EM tomography." (PMID 29727463, 2018). "In another study, Russo and colleagues conducted a genome-scale insertional mutagenesis screen of Hap-1 cells to identify loci involved in promoting an infection by Shigella flexneri." (PMID 30301858, 2018). "Furthermore, 33 (82.5%) of 40 accessions with a resistant reaction to P1 infection belonged to the Hap1 group, and 26 accessions belonged to the indica-I subgroup." (PMID 28355306, 2017). "In addition to RNAi approaches, we also tested the effects of rVSV-SFTSV infection in HAP1 UGCG knockout cells (UGCG KO)." (PMID 28388693, 2017). "Moreover, silencing of eIF2A or eIF2D by transfection of the corresponding siRNAs in HAP1 WT, HAP1-eIF2A− and HAP1-eIF2D− cells had little effect on the synthesis of viral proteins late in infection." (PMID 28240315, 2017). "Single round infection in SupT1 WT or SupT1 EAP45 KO cells using HIV GFP‐expressing virus pseudotyped with VSV‐G shows a modest defect in viral gene expression possibly at a post‐transcriptional level consistent with our published results in HAP1 EAP45 KO cells." (PMID 31922351, 2020). "Using this assay, HAP1 wild type (WT) cells are readily infected by rVSV-ΔG-LASV in an α-DG-dependent manner, whereas HAP1-DAG1- cells resist infection." (PMID 35750689, 2022). "Transduction of HAP1 ADAM9KO cells with mADAM9-E348A and subsequent infection of several clones with EMCV showed that mADAM9-E348A overexpression increases the susceptibility of human ADAM9-deficient cells to EMCV." (PMID 31409686, 2019). "For negative control, we used SEM cells (#) stably depleted of HAP1 by infection with retrovirus carrying pRS-shHAP1 (#+pRS-shHAP1)." (PMID 38721527, 2024). "Upon infection of HAP1 DUX4 knockout (ko) cells, we could not detect DUX4 protein by Western Blot, while as expected it is present in the infected wildtype (wt) HAP1 cells." (PMID 39814710, 2025). "Upon infection of HAP1 DUX4 knockout (ko) cells, we could not detect a DUX4 specific band in the Western Blot, which is present in the infected wildtype (wt) HAP1 cells." (PMID 38168299, 2023).
tumor (14 papers, 1998 to 2024). "In a similar way, a genome wide genetic screen on HAP1 was conducted to uncover tumor-intrinsic genes that regulate tumor killing by major histocompatibility complex-unrestricted cytotoxic lymphocytes." (PMID 36936678, 2023). "Among these genes, it has been reported that EVA1A and HAP1 expression is decreased in tumor tissues, while HIF1α is dramatically increased 36-38." (PMID 32724459, 2020). "The tumor volume in the PAK1-knockout HAP1 cell-injected mice was smaller than that in the HAP1 cell-injected mice." (PMID 31658701, 2019). "All 25 tumours examined showed positive staining for HAP1, but there was heterogeneity in the level of expression both within and between tumours." (PMID 9820167, 1998). "HAP1 expression levels were determined after staining of formalin-fixed paraffin-embedded tumour sections with a rabbit antiserum raised against recombinant HAP1." (PMID 9820167, 1998). "HAP1 promotes apoptosis and controls the malignant transformation of tumor cells." (PMID 38975245, 2024). "Currently, the way in which HAP1 targeting leads to tumor suppression is not well understood." (PMID 38975245, 2024). "Interestingly, of 85 genes whose expressions were reduced in the HAP1 system, 23 genes showed copy number alterations detected in 14 ccRCC tumours (6 G1 and 8 G3 tumours)." (PMID 28486536, 2017). "Similarly, the HAP1 expression in regions of invasive tumour necrosis was cytoplasmic." (PMID 9569057, 1998). "For example, a comparison of GIs with STAG2 KO in 3 different cell lines found only one interaction common to HAP1, RPE1, and tumor-derived H4 cell lines." (PMID 38478595, 2024). "This asRNA is located in the locus containing genes JUP, FKBP10, HAP1, LEPREL4 and EIF1 upregulated in HPV16+ tumours." (PMID 29263803, 2016). "Eliminating or reducing the activity of HUWE1 itself, which reduces WNT/CTNNB1 signaling in WT HAP1–7TGP, CSNK1A1KO and CTNNB1ST-A cells, is unlikely to be a viable therapeutic strategy due to the pleiotropic effects of HUWE1 on cell physiology, including tumor suppressor functions." (PMID 38410441, 2024).
neurodegenerative disease (11 papers, 2012 to 2025). A disorder of the central nervous system characterized by gradual and progressive loss of neural tissue and neurologic function. "Huntingtin-associated protein 1 (HAP1) is a polyglutamine (polyQ) length-dependent interactor with causal agents in several neurodegenerative diseases and has been regarded as a protective factor against neurodegeneration." (PMID 33089002, 2020). "In addition to HD and AD, HAP1 has been highly associated with other neurodegenerative diseases." (PMID 38975245, 2024). "In addition, using animal models that mimic the conditions of certain neurodegenerative diseases (e.g., PD, HD, AD), further study is required to elucidate the precise molecular mechanisms underlying the functional aspects of HAP1, which could be employed in prospective therapeutic applications." (PMID 40766770, 2025). "Due to its stronger binding affinity to mHtt than to normal Htt, the abnormal interactions of HAP1 with mHtt interfere with HAP1-dependent transport in various vesicles or via certain receptors, which results in the onset of neurodegenerative diseases." (PMID 38975245, 2024). "Abnormal interactions of mutant protein with HAP1 affect the intracellular transport of selected molecules, which is an essential contributor to the pathogenesis of neurodegenerative diseases." (PMID 36831801, 2023). "It is believed that HAP1 has putative protective functions against apoptosis/cell death in stress conditions or certain neurodegenerative diseases." (PMID 36831801, 2023). "Several studies have shown that HAP1 function as an autophagy-regulating gene and plays a role in the development of neurodegenerative diseases and neurodevelopmental disorders." (PMID 35459137, 2022). "These brain regions with low Hap1 expression appear to be targets of a variety of neurodegenerative diseases, leading to the idea that Hap1 is protective against neuronal degeneration." (PMID 32581713, 2020). "Taken together, STB/HAP1 is thought to augment the threshold of vulnerability to neurodegenerative apoptosis, confer increased neuronal stability, and subsequently protect against cell death and apoptosis in several neurodegenerative diseases." (PMID 33089002, 2020). "STB/HAP1 enriched areas in the brain/spinal cord are usually protected from neurodegenerative diseases, whereas the regions with tiny amounts or no STB/HAP1 are affected." (PMID 36831801, 2023). "Interestingly, these regions of the central nervous system are usually spared from neurodegeneration, whereas the regions lacking STB/HAP1 or with little expression such as neocortex, striatum, thalamus, cerebellum and spinal motoneurons are major targets in different neurodegenerative diseases." (PMID 33089002, 2020).
neurological diseases (4 papers, 2012 to 2024). "Huntingtin-associated protein 1 (HAP1), the first identified HTT-binding partner, is highly expressed in the central nervous system, and has been found to associated with neurological diseases." (PMID 36824265, 2023). "HAP1 is also a potential therapeutic target for various neurological diseases." (PMID 38975245, 2024). "Moreover, some of the candidate genes have previously been linked to psychiatric and neurological disorders (e.g. RORB, HAP1, HCRTR1 and CABP1), further emphasising the potential importance of these candidate genes in the human brain." (PMID 22384057, 2012).
HAP1 also shares sentences with these, for which no sentence is quoted: Alzheimer disease (3 papers); Anxiety (2); adrenal carcinoma (1); alcoholism (1); cervix carcinomas (1); ciliopathy (1); cognitive decline (1); coronary atherosclerosis (1); cyclosporiasis (1); glioma (1); Hutchinson-Gilford progeria syndrome (1); injury (1); ischemic stroke (1); leptospirosis (1); lung adenocarcinoma (1); mantle cell lymphoma (1); mental disorder (1); metabolic syndrome (1); neurodevelopmental disorder (1); osteosarcoma (1); Parkinson disease (1); prostate adenocarcinoma (1); skin cutaneous melanoma (1); spinocerebellar ataxia 10 (1); Spinocerebellar ataxia type 3 (1); systemic sclerosis (1); T-cell leukemia (1); triple-negative breast carcinoma (1); Williams syndrome (1).